LEP (leptin)
Diseases named in the same sentence as LEP in open-access papers (continued):
Sharing a sentence is not in itself a finding about the gene and the disease.
Obesity (continued). "A key link between obesity and cardiovascular disease is leptin, and hyperleptinemia or leptin resistance in human obesity influence cardiovascular structure and function, inflammatory processes, and sympathetic activity that is stimulated in obese patients with obvious gender differences." (PMID 34757495, 2021). "Leptin is a hormone secreted primarily by adipocytes and evidence suggests that low fetal leptin concentrations may mediate weight gain during infancy and play a role in the development of obesity." (PMID 33681100, 2021). "Adiponectin (APN) and leptin are closely related to obesity." (PMID 34055030, 2021). "Recently, it has been revealed that VEGF-derived hypothalamic astrocytes are directly involved in obesity-induced hypothalamic microvasculature remodeling and elevated systemic blood pressure via sympathetic outflow, an effect dependent on leptin signaling and concomitant with the onset of obesity." (PMID 34822390, 2021). "It is also known that leptin-induced mammalian target of rapamycin (mTOR) activation may have implications for obesity-related pathophysiological conditions such as breast cancer." (PMID 34684340, 2021). "PAQR3 has modulatory roles in obesity, energy metabolism, and leptin signaling." (PMID 33526009, 2021). "In those women, the indicative of obesity was BMI and waist circumference (WC) characteristics of visceral obesity, in addition to positive correlation between the concentration of leptin and WC, between the levels of resistin and insulin and the levels of resistin and HOMA." (PMID 33520042, 2021). "In obese subjects, the sympatho-excitatory effects of leptin on the cardiovascular system are maintained while its metabolic effects result ineffective, suggesting that some form of obesity may be characterized by a “selective leptin resistance”." (PMID 34068919, 2021). "Our study’s benefit is the proof that acute stress decreases leptin levels and thus promotes food intake and may be a pathway towards obesity." (PMID 34684349, 2021). "The diverse mechanisms linking obesity or increased adiposity with HTN are centered on adipose tissue dysfunction characterized by an overproduction of proinflammatory adipokines (such as leptin), and suppression of anti-inflammatory adipokines (such as adiponectin)." (PMID 34684374, 2021). "Also, the fact that the beneficial effect of PI3Kγ ablation on obesity, insulin resistance, and liver steatosis required an intact leptin signalling, suggests a possible role for PI3Kγ activity along the adipocyte–brain axis." (PMID 34704005, 2021). "Adipose tissue hyperplasia during obesity induces the secretion of adipocytokines such as leptin, interleukin-6 (IL-6), interleukin-1β (IL-1β), IL-10, TNF-α, monocyte chemo-attractant protein-1, and plasminogen activator inhibitor-1, which are responsible for obesity-related inflammation." (PMID 33946303, 2021). "One of the key factors that may link obesity and OC is leptin (LEP), known as an adipokine with pleiotropic effects on body homeostasis." (PMID 34884678, 2021). "Leptin is overexpressed at the gene level in the adipose tissue of individuals with obesity." (PMID 34084149, 2021). "In line with the appreciable amount of clinical data illustrating hyperleptinemia as a link between obesity and vascular dysfunction, animal studies using vascular injury models have shown that exogenous leptin promotes neointimal growth and vascular remodeling." (PMID 34064112, 2021). "Given that leptin strongly induces fatty acid biosynthesis in cancer cells, these agents may become a promising candidate for treatment of obesity-related cancer." (PMID 33535537, 2021). "Leptin concentrations are increased, whereas adiponectin levels are decreased in obesity." (PMID 34348687, 2021). "Multiple mechanisms compromising the signaling cascade and action of leptin and its receptor in obesity conditions have been described, although specific pathways remain unclear." (PMID 34899599, 2021).
Obesity (continued). "Thanks to similarities in activity of upds and leptin, Drosophila with genetically induced obesity (e.g., upd1Δ or upd2Δ mutants) might be used as a good model for human obesity." (PMID 34681728, 2021). "A previous study suggested that leptin and adiponectin could modulate the relationship between obesity and IR." (PMID 34925239, 2021). "This indicates that in PWS, alterations of leptin levels and central processing might lead to enhanced food-related reward sensations, thereby stimulating hyperphagia and obesity." (PMID 34768651, 2021). "After the first reports on humans with early-onset severe obesity carrying biallelic likely pathogenic variants in the leptin (LEP) and leptin receptor gene (LEPR), it was clear that a fundamental failure in LEP and LEPR signaling causes a dramatic phenotype." (PMID 34448070, 2021). "Leptin may also play a role in suppressing TSH-induced thyroid function in individuals with obesity." (PMID 33818715, 2021). "Plasma leptin level is considered a key biomarker for obesity and metabolic diseases." (PMID 34879063, 2021). "Leptin resistance is another metabolic dysfunction in obesity." (PMID 33546219, 2021). "More research is needed to fully understand leptin’s role in common obesity." (PMID 34680059, 2021). "This study shows that A. officinarum possesses antihypertensive and diuretic effects possibly mediated through attenuation of obesity markers (weight gain, leptin, and adiponectin), lipid parameters and appreciable diuretic, catalase, and superoxide dismutase activities." (PMID 34305591, 2021). "Like leptin, IL‐6 and TNF‐α are produced and released from human adipocytes, and their elevated levels have been found to be strongly associated with all measures of obesity in other studies from Europe or the United States." (PMID 33680494, 2021). "Concretely, the adipokines, such as leptin, adiponectin, resistin, and other adipokines like visfatin, secreted frizzled-related protein 5 (SFRP5), play an indispensable role in the manipulation of obesity-associated BC." (PMID 34350120, 2021). "On the other hand, diet-induced obesity is thought to arise from the development of central leptin resistance as a result of persistently elevated circulating leptin levels as well as from complex pro-inflammatory processes that directly interfere with hypothalamic leptin receptor signaling." (PMID 34064308, 2021). "Hence, these results indicate that the re-sensitisation of leptin signalling mediated by neutralising antibodies has a promising weight-lowering and thermogenic efficacy, thus making it a potential therapy against leptin-resistant obesity." (PMID 34208585, 2021). "Therefore, more studies in the mechanism of leptin are warranted to investigate the immune response in COVID-19 patients with obesity." (PMID 34220807, 2021). "In the present study, we demonstrate that a novel isolated B. longum APC1472 strain, which was previously shown to attenuate ghrelinergic signalling, reduces body weight gain, fat depot size, glucose tolerance and leptin levels in a preclinical mouse model of HFD-induced obesity." (PMID 33349590, 2021). "Our findings suggest that obesity plays a role in chronic inflammation (as seen in leptin and IL-6 levels modified by BMI) while the additional inflammatory pressure resulting in elevated NOV and EPC levels is likely driven by intermittent hypoxia and inflammation specific to OSA pathophysiology." (PMID 34868456, 2021). "Leptin is an important mediator to linking obesity and a variety of obesity related tumors." (PMID 34485124, 2021). "The discovery of the hormone leptin almost 3 decades ago was particularly exciting, offering hope that obesity could be treated by modulating leptin signaling." (PMID 34231322, 2021). "Indeed, leptin is an adipose tissue-derived hormone which acts an appetite suppressant, and is strongly correlated with body mass index and obesity." (PMID 31796892, 2021).
Obesity (continued). "Moreover, SAT expression of VIRMA is consistently negatively correlated with WHR, body fat percentage, adipocyte diameter and leptin levels, all being clinical variables related to fat distribution and obesity." (PMID 34950106, 2021). "We also recently reported that polymorphisms at LEP, LEPR, and MC4R may be useful markers of obesity-related cardiometabolic alterations in a cohort from South Chile." (PMID 33540559, 2021). "Interestingly, these and other proinflammatory cytokines themselves induce leptin release from adipocytes, creating a vicious cycle of inflammation and leptin secretion, especially when adipocytes are numerous and dysfunctional such as in obesity." (PMID 34436472, 2021). "Thus, an unfolded protein response ensues, leading to insulin and leptin resistance and subsequently, to obesity and its metabolic consequences." (PMID 33562540, 2021). "A study in Mexico City demonstrated possible mechanisms in children associated with the development of obesity that included differences between exposed and non-exposed children in leptin, endothelin-1, glucagon-like peptide-1 (GLP 1), ghrelin, and glucagon." (PMID 33652701, 2021). "Decreased adiponectin and increased leptin resistance in obesity result in insulin resistance, dysfunctional lipid metabolism, atherosclerosis, and the activation of proinflammatory cytokines and oxidative stress, which lead to vascular hypo-perfusion and chronic inflammation of RGCs." (PMID 34501469, 2021). "Leptin has been dismissed as the main treatment for obesity with resistance." (PMID 33776757, 2021). "The observation that PRMT2 null mice are leaner than wildtype animals, associated with perturbed energy metabolism, resistance to obesity and enhanced leptin sensitivity, suggested an involvement of PRMT2 in the regulation of feeding via a leptin-dependent pathway." (PMID 34833139, 2021). "The LEP gene has globally been reported to contribute to the pathogenesis of obesity." (PMID 34131278, 2021). "Collectively, the evidence suggests leptin may play a role in neuroprotection and the effects of obesity on neurodegenerative disorders." (PMID 34497507, 2021). "Leptin levels are elevated in obesity and chronic inflammatory responses." (PMID 34202165, 2021). "Collectively, the data suggest that RSV could reverse hyperleptinemia and improve central leptin action in adult offspring from HF mothers, thus attenuating obesity." (PMID 34209270, 2021). "Thus, to summarize, we can argue that several factors associated with obesity increase the risk for CAC, including elevated leptin levels, increased PAI-1 levels, endothelial dysfunction and low vitamin K levels." (PMID 33920604, 2021). "It is possible that some features of obesity, including increased levels of fatty acids and leptin, may contribute to greater decline in kidney function in those who develop diabetes at younger age20,21." (PMID 34282181, 2021). "This study reported the relationship between TCMBC, leptin, and obesity-related SNPs." (PMID 34055005, 2021). "Obesity leads to ovarian dysfunction and the establishment of local leptin resistance." (PMID 34805147, 2021). "The higher leptin levels present in individuals with obesity may play a role in the severity of COVID-19." (PMID 34047810, 2021). "Indeed, during obesity, the adipose tissue secretes adipokines other than leptin with potential consequences for ovarian function regulation." (PMID 33924072, 2021). "This balance is lost in obesity and insulin resistance since cellular sensitivity to circulating leptin is diminished in target receptors (i.e., in the arcuate and ventromedial nuclei, as well as other parts of the hypothalamus and dopaminergic neurons of the ventral tegmental area (VTA))." (PMID 34660808, 2021).
Obesity (continued). "It was reported that the increased level of leptin in obesity could promote BC initiation, progression, metastasis, and resistance to therapy through a variety of mechanisms including the activation of PI3K/Akt, JAK/AKT/STAT, and FAK-Src signaling pathway." (PMID 34350120, 2021). "Resistance to the hormone leptin is a feature common to obesity." (PMID 34574696, 2021). "Dysfunction of cytokines and hormones such as leptin, ghrelin, insulin, GLP-1, resistin, and visfatin has been implicated causally in the pathogenesis of obesity but also as a mediator between excess fat mass and insulin resistance, T2D, and cardiovascular disease." (PMID 34620218, 2021). "The increase in leptin during infancy thus increases the prevalence of obesity." (PMID 34568497, 2021). "Leptin is proposed to affect blood pressure through its sympathetic activity and leptin levels directly associated with blood pressure changes in rodent models of obesity, which is not seen in models of leptin deficiency." (PMID 34966295, 2021). "Besides, leptin also correlates with many obesity parameters, and its secretion also increases with the enlargement of adipose tissue." (PMID 34568404, 2021). "However, this leptin level was approximately 13 times higher than that measured in our study (2.1 ng/mL) due to differences in study populations (obesity vs. EGC)." (PMID 34501456, 2021). "This hypothesis is supported by mouse studies showing an effect of obesity on oocyte polarization, reactive oxygen species levels and DNA methylation, including methylation of metabolism-related genes, such as the leptin promotor region." (PMID 34537064, 2021). "Some research has found a significant correlation between leptin messenger RNA (mRNA) expression in cartilage in patients with advanced OA and BMI, suggesting that leptin could serve as a metabolic link between obesity and OA." (PMID 33803785, 2021). "Early on, even prior to the clinical diagnosis of T2DM, there may be variable degrees of obesity, insulin and leptin resistance and impaired glucose tolerance." (PMID 34063911, 2021). "Our data may stimulate further human genetics research to test the hypothesis that compound heterozygous variants in the Leptin and or LEPR genes contribute to an increased obesity risk in subpopulations." (PMID 34390703, 2021). "LEP G2548A is not the only variant implicated in the development of obesity and related metabolic derangements." (PMID 34208585, 2021). "The low incidence of leptin-specific mutations in humans indicates that genetic abnormalities in the leptin system are not the principal route for the development of obesity in humans." (PMID 33440796, 2021). "Consequently, hypoleptinemia is seen in states of malnutrition whilst obesity is characterized by hyperleptinemia and leptin desensitization." (PMID 33927722, 2021). "Obesity is characterized by hyperphagia and decreased energy consumption due to leptin resistance." (PMID 34306972, 2021). "Individuals with mutations in the leptin gene, regardless of their obesity status, have been treated with exogenous sources of leptin to restore normal function." (PMID 34899599, 2021). "For example, leptin could induce vasodilation to modulate blood pressure homeostasis; however, obesity-induced hyperleptinemia resulted in an increase of endothelin-1, which then leads to vasoconstriction." (PMID 34239444, 2021). "These metabolic alterations, including the rising systemic insulin resistance, increased plasma leptin levels, and obesity may impair vascular function in large vessels only in a longer treatment model." (PMID 33791074, 2021). "Increased concentrations of circulating leptin in obesity are known to increase neuroendocrine dysfunction exacerbated by hypothalamic leptin resistance, which leads to the down regulation of appetite-suppressing and energy-expending signals, contributing to obesogenic conditions." (PMID 34497507, 2021).
Obesity (continued). "Interestingly, another study also in MCF7 cells found that estrogen increases leptin and Ob-R mRNA, potentially representing a positive feedback loop between leptin and estrogen that amplifies expression of both in obesity." (PMID 33859943, 2021). "Additionally, the hypothalamus of obese subjects was also found to be characterised by the presence of oxidative stress, which leads to the depletion of POMC neurons, and, consequently, to the induction of systemic leptin resistance and obesity." (PMID 34208585, 2021). "Obesity-induced inflammation, insulin resistance and high plasma leptin promote an impairment of synthesis of nitric oxide (NO) producing an imbalance between vasodilatation and vasoconstriction, favoring arterial stiffness and vascular remodeling what promotes arterial hypertension." (PMID 33928108, 2021). "In the case of obesity however, plasma leptin levels have been found to be elevated." (PMID 33802480, 2021). "In the context of multifactorial and polygenic obesity, LEP/LEPR heterozygosity may represent an underdiagnosed factor." (PMID 34448070, 2021). "It seems that sleep deprivation and sleep disorders may through alterations in hormonal status such as increase in ghrelin level and decrease in leptin level lead to obesity, metabolic dysregulation and obesity-related complications." (PMID 34819076, 2021). "While we did not measure food intake in the current study, leptin signaling deficient models of obesity eat more food than their lean control counterparts." (PMID 34975523, 2021). "Therefore, lower serum leptin delays the feeling of satiety during eating and leads to more energy intake and develops obesity." (PMID 34243821, 2021). "Studies have shown that mice fed with a high-fat diet developed obesity and leptin resistance." (PMID 34943840, 2021). "Only 33 mRNAs among 185 mRNAs overlapped between the 3945 four miRNAs-associated mRNAs and the 475 obesity-associated mRNAs were statistically associated with leptin with 21 positive and 11 negative associations (p < 0.05 for all)." (PMID 34440082, 2021). "Our findings suggests that leptin may have implications in obesity development in response to stress in a sex-dependent manner." (PMID 34684349, 2021). "In this regard, the prevention and reversion of leptin resistance may represent an important challenge in the field of obesity treatment; yet, the main results to date are derived from animal models." (PMID 34208585, 2021). "Insufficient sleep can increase food intake through organizing some neuroendocrine, for example, changes in leptin and ghrelin concentrations and other metabolic and behavioral compatibility so weight gain and inflammatory status such as obesity may occur." (PMID 34760255, 2021). "Also, a better improvement in food intake and weight was observed in some obesity treatments in female mice, representing a sexual dimorphism probably dependent of leptin effects." (PMID 33980961, 2021). "Interestingly, leptin, the primary regulator of appetite and energy homeostasis is related to insulin resistance and the development of obesity when produced in excess." (PMID 34497507, 2021). "Leptin/adiponectin ratios correlated with arterial stiffness and obesity." (PMID 34680168, 2021). "Furthermore, both increases in leptin and a diminution of adiponectin signaling likely contribute to obesity-related HFpEF." (PMID 33809061, 2021). "While leptin serves as satiety signaling in the context of energy surplus, chronic hyperleptinemia may lead to blunted responses and obesity." (PMID 35127598, 2021). "Therefore, for obese patients, the overexpression of leptin and leptin receptors is the key to the development of various obesity-related tumors." (PMID 34485124, 2021). "One of the most studied pathways in the history of obesity research is the leptin cascade." (PMID 33572982, 2021).